Y_RNA (Y RNA )
Gene: Miscellaneous RNA gene on chromosome 5 (168,791,498 to 168,791,610, forward strand). Ensembl gene ENSG00000202345.
Homologues: Orthologues: chimpanzee Y_RNA (100% identical), macaque Y_RNA (99% identical). Paralogues in human: RNY1 (90% identical), Y_RNA (86% identical), Y_RNA (85% identical), RNY1P11 (84% identical), Y_RNA (84% identical), Y_RNA (83% identical), RNY1P10 (82% identical), RNY1P8 (82% identical), Y_RNA (82% identical), Y_RNA (81% identical), Y_RNA (80% identical), Y_RNA (79% identical), and 96 more.